IL6 (interleukin 6)
Diseases named in the same sentence as IL6 in open-access papers (continued):
Sharing a sentence is not in itself a finding about the gene and the disease.
breast cancer (continued). "Furthermore, our results are consistent with previous studies where sympathetic stimulus increases IL-6 production in breast cancer and melanoma cell lines in vitro." (PMID 35243294, 2022). "Additionally, CM and its EXOs inhibited IL6, TNFα, and NFκB expression in spleens of immunocompromised rats and mammary tumor tissues." (PMID 36363614, 2022). "Furthermore, administration of recombinant IL-6 induced chemoresistance through upregulation of drug-resistant gene, mdr1, in breast cancer cells." (PMID 35371975, 2022). "Inhibition of CK2 decreases secretion of IL-6 in breast cancer cells and mouse macrophages." (PMID 35774866, 2022). "IL-6 also functions in a paracrine manner to promote an invasive phenotype in breast cancer." (PMID 35371975, 2022). "Furthermore, activation of the IL-6 inflammatory loop induces trastuzumab-resistance in HER2+ breast cancer cells indicating that IL-6’s pro-inflammatory role mediates breast cancer therapeutic resistance." (PMID 35371975, 2022). "Exosomal glycoprotein-130 (gp130) obtained from breast cancer cells was also observed to contribute to the progression of cancer through the activation of the IL-6/STAT3 pathway in macrophages thus leading to the alteration of normal macrophage phenotypes into pro-cancer phenotypes." (PMID 36406206, 2022). "In sum, 4T1 mammary carcinomas secrete IL-6 and other factors, to polarize and reshape Th populations and expand distinct Th17 and Th22 populations, which may facilitate tumor growth and confer immunotherapy resistance." (PMID 36142210, 2022). "IL-6 and IL-8 function as downstream targets of Egr3 in breast cancers." (PMID 34234781, 2021). "In addition, the approach through which IL6/STAT3 regulates breast cancer development is thought to be by promoting Jak and angiogenesis signaling, which has been documented recently." (PMID 34833950, 2021). "In patients with breast cancer, the administration of paclitaxel or docetaxel increases the serum levels of IL-2, IL-6, IFN-γ, and granulocyte macrophage colony-stimulating factor (GM-CSF) and peripheral NK cell activity, whereas NAC decreases the levels of IL-1 and TNF-α." (PMID 34638242, 2021). "In breast cancer model of MCF7 and MDA-MB-468, autophagy-deficient cells restore mammosphere formation with the supplementation of IL6 or treatment of conditioned media from autophagy competent cells, suggesting that autophagy is required for the secretion of IL6 to maintain cancer stem cells." (PMID 33743781, 2021). "In another research, IL-6 treatment could help breast cancer cells exit from dormancy mediated by hormone therapy by activation of Notch3." (PMID 33771156, 2021). "The findings indicate the involvement of polymorphisms of the IL-6, C-X-C motif chemokine ligand 8 (CXCL8), and TNF genes and modification of methylation in the TNF gene promoter favoring the occurrence of chronic breast pain after breast cancer surgery." (PMID 34685397, 2021). "As many proinflammatory cytokines, including IL-1β, IL-6, and TNF-α, have been strongly linked to breast cancer progression, their suppression could be a key mechanism mediating the chemoprotective role of phytoestrogens in this cancer." (PMID 35008370, 2021). "Chemotherapy triggers expression of IL-6 and TNF-α in endothelial cells, fostering a pro-tumor inflammatory microenvironment (IL-6) and conferring chemoresistance to breast cancer cells (TNF-α); at the same time, endothelial cells gain chemoresistance by exposure to bFGF and VEGF present in the TME." (PMID 34439387, 2021). "It has been demonstrated that KYNA binding to AHR induces IL-6 production in breast cancer cells." (PMID 33422134, 2021). "Moreover, NF-κB pathway activation is proved to be important for the paracrine function of tumor-derived-MSCs and cancer-associated fibroblasts in lung cancer and breast cancer in secreting CCL2, IL-6, and IL-8 in the tumor microenvironment." (PMID 33889575, 2021).
breast cancer (continued). "Furthermore, increased levels of IL-6 were correlated with poorer prognosis in many cancer types, including breast cancer, prostate cancer, metastatic CRC, MM, and non-small cell lung cancer (NSCL]." (PMID 34768810, 2021). "Moreover, in a recent study on patients receiving neoadjuvant chemotherapy for locally advanced breast cancer, serum IL-6 levels were significantly higher before, during and after termination of chemotherapy." (PMID 33886107, 2021). "Furthermore, hypoxia-inducible factor 1α (HIF1α) downregulated breast CSCs by reducing the IL-6 levels in breast cancer cells expressing Notch3." (PMID 33673088, 2021). "Many cytokine and growth factor receptors trigger JAK1/2-STAT3/5 activation, however, it was somewhat unexpected and striking that a GPCR such as DOR could also activate STAT3 in breast cancer cells to a similar extent as IL-6 cytokine stimulation." (PMID 33465556, 2021). "In oesophageal and breast cancer cells, IL-6 exposure has been shown to promote mesenchymal/fibroblastic morphology, migration and invasion in vitro and in vivo, associated with reduced CD24, KRT19, EpCAM and E-cadherin expression and increased vimentin, N-cadherin and MMP9 levels." (PMID 34361105, 2021). "Alshaker and colleagues demonstrated that leptin as an adipokine was able to induce upregulation of SPHK1 and in turn SPHK1 could contribute to leptin-induced STAT3 activity in breast cancer via transactivation of IL-6/gp130." (PMID 34820423, 2021). "We found here that genistein inhibited Il6 expression in the mammary tumors in the HFD offspring." (PMID 33440675, 2021). "The researchers propose that, by decreasing the activity of NF-κB and ultimately plasma IL-6, fatigue may improve in breast cancer patients taking Meriva." (PMID 34298639, 2021). "Consistently, the previous study has proved that IL-6 could promote tumor growth and metastasis, and high expression of IL-6 in breast cancer is related to the degree of lymph node involvement and TNM stage, indicating poor prognosis." (PMID 34165442, 2021). "Thus, FRH inhibits IL-1β and IL-6 mRNA expression in these breast cancer cells in a temperature-dependent manner." (PMID 34201348, 2021). "Adipocyte-associated secretion of IL-6 also participates in the Notch/Wnt/TGF-β signaling pathways by upregulating ALDH1A1 and LEF1 and AXIN2 gene expression in the Wnt pathway to enhance the invasiveness, metastasis and angiogenesis of breast cancer." (PMID 34202411, 2021). "Interestingly, an autocrine feedback loop is generated in tumor cells to enhance an inflammatory phenotype, since SNAIL and ZEB1/2 are able to activate IL6 expression in head and neck squamous carcinoma and breast cancer." (PMID 34459003, 2021). "The inhibition of IL-6 activity by specific antibodies in combination with chemotherapy successfully induced an almost complete regression in a PDX model of breast cancer by interrupting the inflammatory loop between the IL-6 and STAT-3 responsible for the EMT and stemness maintenance." (PMID 33916320, 2021). "This is in line with the conceptual goals of Optimune, as regular aerobic exercise seems to reduce inflammatory markers, such as CRP, TNF-α, and Interleukin-6, and reducing chronic inflammation may improve the prognosis of breast cancer survivors." (PMID 33961667, 2021). "Finally, the study of polymorphisms of inflammatory mediators such as the IL6, CXCL8, and TNF genes deserves attention because it can be helpful in the choice of the proper pain therapy for the postoperative period following breast cancer surgery." (PMID 34685397, 2021). "In addition, a Phase 2 randomized trial of perioperative propranolol, a β-blocker, and etolodac in breast cancer patients reported normalization of IL-6 and CRP, decreased EMT, and decreased tumor-infiltrating monocytes." (PMID 34768810, 2021).
breast cancer (continued). "Previous study also showed that the activation NF-KB signaling pathway in breast cancer cells could upregulate interleukin-6 expression, and further promote cancer cell metastasis." (PMID 34267752, 2021). "We have successfully illustrated that targeting IL-6R could be an alternative way to suppress IL-6/STAT3 pathway in breast cancer and demonstrate the usage of TCZ could reduce tamoxifen resistance in breast cancer." (PMID 33806019, 2021). "Hence, breast cancer cells induce adipocytes IL-6 secretion, which is in turn responsible of the higher breast cancer aggressiveness." (PMID 33751362, 2021). "Furthermore, studies have suggested that SPHK1/S1P/S1PR1 signaling pathway also aids to mediate treatment-induced inflammation and resistance to doxorubicin and tamoxifen in breast cancer, which is also accompanying with upregulation of NF-κB/IL-6/STAT3." (PMID 34820423, 2021). "Interestingly, IL-1ß and IL-6 have been shown to increase focal adhesion kinase (FAK) in breast cancer cells." (PMID 33809315, 2021). "Importantly, several reports suggest that both IL-6 and IL-8 play a critical role in the aggressiveness of breast cancer and of other types of cancer." (PMID 34445170, 2021). "Interestingly, depending on the breast cancer subtype, autophagy decreases IL6 secretion and thereby possibly reduces BCSC numbers." (PMID 34207792, 2021). "Similarly, osteoblast-derived cytokines including IL-6 and IL-8 have been reported to stimulate the migration of breast cancer cells in vitro." (PMID 33809315, 2021). "In TNBC, IL-6 plays a critical role in breast cancer growth and maintenance." (PMID 34067421, 2021). "Importantly for breast cancer, aromatase—the rate-limiting enzyme for estrogen biosynthesis—is stimulated in the adipose tissue by adipose-derived factors (IL-1β, IL-6, TNF-α, and prostaglandin (PG) E2) as well as liver-derived IGF-1." (PMID 34066392, 2021). "Furthermore, IL-6 promotes breast cancer metastasis through upregulation of lysyl hydroxylase-2, an enzyme, which levels in the tumor correlate with poor prognosis in breast cancer patients." (PMID 34944905, 2021). "Furthermore, Sabutoclax not only causes the release of caspase from mitochondria to cause cancer cell apoptosis, but also blocks the interleukin 6/signal transducers and activators of transcription (IL-6/STAT) pathway to eliminate the breast cancer stem cells." (PMID 33816265, 2021). "Thus, an IL-6 signaling loop between breast cancer cells and myeloid derived suppressor cells that drives cancer cell invasiveness and distant metastasis has been proposed." (PMID 33809315, 2021). "Additionally, patients with multiple sites of breast cancer metastases had higher serum IL-6 levels compared to patients with one documented metastatic site." (PMID 33809315, 2021). "The efficacy of sunitinib as an anti-EMT target therapy has been proven in claudin-low human breast cancer cell lines, and this drug may be able to take advantage of IL6 inhibition." (PMID 34775465, 2021). "Moreover, in renal clear cell carcinoma, NSCLC, colon and breast cancer IL6 and IL35 are produced by macrophages and promote EMT by prostaglandin/β‐catenin and JAK2‐STAT6‐GATA3 signaling, respectively." (PMID 34459003, 2021). "However, the activation of IL6/STAT3 pathway which was found in a brand-new study promoted the metastasis of ER+ intraductal breast cancer in vivo, and it strikingly constituted another oncogenic pathway which was relatively independent of ER pathway." (PMID 34717710, 2021). "Several studies have examined the potential role of IL-6 in breast cancer progression." (PMID 34944905, 2021). "In breast cancer, IL-6 pre-treatment followed by SIRT1 activation by SRT1720 combined with dual PI3K/mTOR inhibitor NVP-BEZ235 obviously increased sensitivity of the cancer stem cells to radiation, so that late stage breast cancer cells therapeutic effect was effectively improved." (PMID 33790792, 2021).
breast cancer (continued). "In addition, IL-6 induces breast cancer cell proliferation indirectly through an increase in estrogen at the tumor site, for example, through activation of the enzyme aromatase." (PMID 34944905, 2021). "The presence of a high-risk IL-6 promoter genotype polymorphism is strongly and significantly associated with relapsed HR+/HER2+ breast cancer, and may have important therapeutic implications." (PMID 33483516, 2021). "IL-6 from adipose stromal cells can promote breast cancer cell proliferation and migration." (PMID 34621683, 2021). "Consistently, IL-6 is known to play a crucial role in STAT3 activation in breast cancer." (PMID 34833950, 2021). "On the other hand, IL-6 has been demonstrated to enhance breast cancer resistance to chemotherapy; thus, targeting IL-6 could increase breast cancer sensitivity to chemotherapy." (PMID 33517609, 2021). "In the current study, we demonstrate that BQ overexpression could enhance the expression of IL-6 and IL-6R, which in turn activates the IL-6/STAT3 pathway to mediate tamoxifen resistance in breast cancer." (PMID 33806019, 2021). "Indeed, PROM1 has been shown to mediate endocrine therapy resistance in breast cancer models through IL6/Notch3 signaling." (PMID 33407744, 2021). "The authors suggested that IL6 could be used as a predictive marker to determine the toxicity of certain breast cancer treatments and may be a precursor to full geriatric assessment, a strategy that is recommended in the field of geriatric oncology." (PMID 34165702, 2021). "Similarly, RB1 inactivation in breast cancers enhances stem cell-like behaviors and malignant progression through IL-6 and following activation of signal transducer and activator of transcription 3 (STAT3) activation." (PMID 34359636, 2021). "Besides IL-1, IL-6, IL-8 and IL-11, other ILs have been investigated in the context of breast cancer bone metastasis." (PMID 33809315, 2021). "The inclusion of cancers other than breast cancer may have influenced the findings for IL-6 and IL-8, but Khosravi did show that CRP and TNF were more sensitive to exercise changes." (PMID 34777343, 2021). "Apart from the significant role of IL-6 in invasion, migration, and thus metastasis in breast cancer, IL-6 induces proliferation in MCF-10 ductal carcinoma in situ (DCIS) cell lines, which could contribute to the progression of DCIS to invasive breast cancer." (PMID 34944905, 2021). "Breast cancer patients showed higher levels of IL-6 in their serum than healthy people." (PMID 31963587, 2020). "Moreover, our team showed that CAFs protect luminal breast cancer cells from apoptosis by upregulating the anti-apoptotic MCL-1 in cancer cells via a paracrine IL-6 signaling, which triggers ERK phosphorylation." (PMID 33080792, 2020). "Interestingly, IL6 is also required for the growth and tumor promoting effects of breast cancer fibroblasts and fibroblasts from common sites of breast cancer metastasis (bone, lung) on ER-positive cancer cells in vitro and in vivo." (PMID 32399610, 2020). "However, invasive melanoma cells were associated with AKT1 signaling related to the migration pathway, squamous cells with the EGFR signaling in response to extracellular cues and breast cancer cells with IL-6 signaling involved in the inflammatory response." (PMID 33142759, 2020). "Higher expression levels of IL-6 and IL-8 contribute to TNBC proliferation and metastasis and, moreover, a higher expression of IL-6 is associated with chemotherapy resistance in breast cancer." (PMID 32806551, 2020). "In addition, several strategies to disrupt IL-6 signaling or IL-8 signaling, in vitro or in vivo, significantly reduce tumor growth and metastasis in breast cancer cells." (PMID 33114046, 2020). "Furthermore, a range of paracrine signaling factors and altered gene expressions explain how CAAs alter the metabolic phenotype of breast cancer cells, including overexpressing proteases and elevating adipokines, including interleukin 6 (IL-6)." (PMID 32296646, 2020).
breast cancer (continued). "Similar to IL-6, increased circulating levels of TNFR2 may influence breast cancer risk through its effect on the estrogen pathway." (PMID 33004039, 2020). "Importantly, the abundance of Faecalibacterium was decreased in breast cancer women and we also found that Faecalibacterium prausnitzii supernatant can suppress the growth of breast cancer cells through the inhibition of IL-6/STAT3 pathway." (PMID 32272885, 2020). "In addition, STAT3 knockdown or JAG1 knockdown reduced the secretion and protein expression of IL-4 and IL-6 in breast cancer cells, it also inhibited the proliferation of breast cancer cells." (PMID 32943090, 2020). "Therefore, while there is a large amount of variation in the extent to which IL-6 inhibits proliferation, the overwhelming body of evidence suggests that IL-6 inhibits breast cancer cell proliferation in 2D cultures." (PMID 32023849, 2020). "Besides, IL-6 has been considered as a primary factor affecting the resistance of breast cancer to trastuzumab, a targeted therapeutic HER2 antibody." (PMID 33123472, 2020). "Therefore, we tested the effect of breast cancer cells and IL-6 on the expression of ATR in BSFs, and have shown that breast cancer cells as well as pure recombinant IL-6 downregulate ATR in BSFs." (PMID 32414408, 2020). "Moreover, there is a direct interplay between the oncoprotein Y-box binding protein-1 (YB-1) and IL-6, which affects breast cancer metastasis." (PMID 33123472, 2020). "The EMT process can be triggered by IL-6 and IL-8 in breast cancer and CRC cells 68,69." (PMID 32641980, 2020). "Meanwhile, the renewal of cancer stem cell could be induced by IL-6 through Notch3 in breast cancer." (PMID 32028262, 2020). "Thus, IL-6 seems to be an attractive target for therapy to cure trastuzumab-resistant breast cancers." (PMID 32483313, 2020). "Moreover, a recent study reported that circulating fatty acid-binding protein released by adipose tissue (A-FABP or FABP4) promotes breast cancer stemness by activating the IL-6/STAT3/ALDH1 pathway." (PMID 32913185, 2020). "Moreover, Interleukin-6 (IL6) function has been reported to be important in the growth and metastasis of breast cancer cells and drug resistance of breast cancer stem cells." (PMID 32577155, 2020). "The interleukins IL-6 and IL-8 facilitate the growth of breast cancer epithelial cells." (PMID 32411704, 2020). "Specifically, DUB3 was shown to respond to IL-6-stimulated transcriptional activation and stabilize Snail1 in breast cancer cells; while USP27X expression was reported to be induced by TGFβ, which assisted the upregulation of Snail1 and other mesenchymal genes." (PMID 32968046, 2020). "EMT was induced in the breast cancer cells by IL-6 treatment." (PMID 33659239, 2020). "Moreover, breast fibroblast cells secrete IL-6, which can increase proliferation and invasiveness of oestrogen receptor positive cells, such as breast cancer MCF7 cells." (PMID 31963587, 2020). "Furthermore, the IL-6/JAK/STAT3 pathway has been shown to be important for the proliferation of CD44+CD24− stem cell–like breast cancer cells." (PMID 32328465, 2020). "Intriguingly, STAT3, AKT, integrin β1 and Bcl-3 are linked to the activities of CSCs or embryonal stem cells, while CAF-CM and IL-6 are able to upregulate the RNA level of the CSC marker ALDH1A1 and while IL-6 has the potential to increase CSC activity in breast cancer cells." (PMID 33228022, 2020). "Therefore, and in line with our results for breast cancer DCCs, IL-6 trans-signaling via binding of IL-6 to sIL-6RA and subsequent binding to gp130 is much more likely involved in pathway activation than classical IL-6 signaling." (PMID 33020483, 2020). "Adipocyte-secreted leptin and IL-6 have a paracrine effect on nearby breast cancer cells." (PMID 32033341, 2020).